FGF23 (fibroblast growth factor 23)
Diseases named in the same sentence as FGF23 in open-access papers (continued):
Sharing a sentence is not in itself a finding about the gene and the disease.
atherosclerosis (continued). "Klotho, a protein that exists in two forms, membrane-bound Klotho and soluble Klotho, and acts as co-receptor for fibroblast growth factor 23 (FGF23), has been shown to be involved in atherosclerosis and cardiovascular disease." (PMID 37061530, 2023). "FGF-23 is a widely studied biomarker, which has been proved to be closely related to atherosclerosis, calcium and phosphorus metabolism disorder and renal function progression in patients with CKD." (PMID 36237550, 2022). "The top five clusters were “calciprotein particles,” “transcatheter aortic valve replacement,” “calcified aortic valve disease,” and “fibroblast growth factor 23,” “vascular smooth muscle cells” and “atherosclerosis”." (PMID 34335257, 2021). "High circulating levels of FGF-23 have been associated with cardiovascular pathophysiologic events, such as LVH, endothelial dysfunction and atherosclerosis." (PMID 33767635, 2021). "The FGF23 levels in patients with sub-clinical atherosclerosis were higher than those with CA-IMT < 0.9 mm patients (85 pg/mL, vs. 69 pg/mL; p < 0.05)." (PMID 32257685, 2020). "Patients with atherosclerosis and vascular calcification presented increased levels of FGF23 respect to the control group." (PMID 31542779, 2019). "Over the last decade, CKD-related mineral and bone disorder (CKD-MBD) involving fibroblast growth factor 23 (FGF23), and calcium and phosphate metabolism, has attracted attention as a new risk factor for progression of atherosclerosis and CKD." (PMID 29996526, 2018). "For instance, serum level of Fibroblast Growth factor 23, a biomarker of atherosclerosis, was positively correlated with the occurrence of PAD in chinese T2D patients." (PMID 29879997, 2018). "Because IMT can serve as an indicator of early atherosclerosis, our findings suggest the application of serum FGF23 levels for indicating clinical atherosclerosis in the early stage." (PMID 28619026, 2017). "Accumulating clinical evidence indicates a link between serum FGF23 levels and atherosclerosis, which is also supported by our previous findings." (PMID 28619026, 2017). "In individuals with a first-degree FHD, serum FGF23 levels need to be higher to indicate the presence of subclinical atherosclerosis." (PMID 27698482, 2016). "Compared to those without an FHD, participants with a first-degree FHD need higher levels of serum FGF23 to indicate the subclinical atherosclerosis." (PMID 27698482, 2016). "Subjects with a first-degree FHD need higher serum FGF23 levels to indicate subclinical atherosclerosis." (PMID 27698482, 2016). "Thus, it is reasonable to think FGF23 could play an important role in the vascular calcification process, since vascular calcification is associated with atherosclerosis, which may help explain the association between elevated FGF23 and the severity of atherosclerotic stenosis." (PMID 26459301, 2015). "Despite of the differences, both studies found a graded relationship between FGF23 and severity of atherosclerosis." (PMID 24015259, 2013). "Data supporting a potential link between FGF-23, atherosclerosis, and measures of obesity are limited." (PMID 23351146, 2013). "Other populational studies have also shown that FGF23 is related to atherosclerosis, mortality, and cardiovascular events." (PMID 22590632, 2012). "In addition, researchers from Turkey believed that FGF23 can also be used as a noninvasive predictor of subclinical atherosclerosis in patients with gestational diabetes." (PMID 38622690, 2024). "Previous clinical studies have shown that FGF23 and α-klotho have highly valuable predictive effects on cardiovascular disease (CVD) in patients with T2DM, but atherosclerosis, the initial cause of cardiovascular events, has received relatively little attention." (PMID 38622690, 2024).
atherosclerosis (continued). "FGF23 appeared to be toxic to endothelial cells, whereas α-klotho appeared to be protective, and the inhibitory effect of FGF23 on α-klotho prompted us to further investigate the effect of the FGF23/α-klotho ratio on atherosclerosis in T2DM, which has received little attention." (PMID 38622690, 2024). "Second, we explored the relationships of FGF23, α-klotho and FGF23/α-klotho ratio with atherosclerosis in Chinese patients with T2DM, and whether FGF23 or α-klotho can be diagnostic and predictive biomarkers for atherosclerosis in T2DM patients." (PMID 38622690, 2024). "The interrelationship between FGF23 and inflammation opens new research pathways regarding the development and progression of atherosclerosis in subjects with CKD, with translational clinical applicability from diagnostic, prognostic, and therapeutic perspectives focused on modulating FGF23." (PMID 38791495, 2024). "FGF23 is involved in atherosclerosis-related damage through advanced vascular plaque calcification." (PMID 34095143, 2021). "For example, FGF-23 is reported to be an independent factor for increased stage of peripheral vascular calcified atherosclerotic plaque and carotid artery intima-media thickness, and is responsible for the development and progression of atherosclerosis." (PMID 33413149, 2021). "FGF23 all by itself causes atherosclerosis and increased arterial stiffness in rodents, non-uremic subjects and CKD, with a resulting elevation in pulse pressure." (PMID 32257685, 2020). "Our findings suggest that monitoring serum FGF-23 may be useful as a non-invasive indicator of subclinical atherosclerosis in patients with GDM." (PMID 30462803, 2018). "Association of FGF-23 with CIMT may be another possible mechanism underlying the development and progression of atherosclerosis in patients with GDM." (PMID 30462803, 2018). "Therefore, we believe that FGF-23 plays a role in the pathogenesis and development of preclinical atherosclerosis and cardiac dysfunction in patients with GDM." (PMID 30462803, 2018). "It was demonstrated that FGF23, nuclear factor-Kb and fetuin A etc might mediate the linkage of calcium phosphate disorder and atherosclerosis." (PMID 27992532, 2016). "In the pathogenesis of atherosclerosis, the potential role of FGF23 may be partially explained through its involvement in the complex process of vascular calcification." (PMID 26459301, 2015). "The potential role of FGF23 in the pathogenesis of atherosclerosis may be partly explained through its involvement in the complex process of vascular calcification." (PMID 24015259, 2013). "Because high FGF23 correlates directly with total body atherosclerosis, it is possible that high FGF23 enhancement of atheromatous disease progression may also contribute to VC." (PMID 24119158, 2013). "One major explanation for that is that renal dysfunction was not an exclusion criteria in the PIVUS and the positive relationship between FGF23 and atherosclerosis might result from that, particularly in older patients." (PMID 22590632, 2012). "In addition, analyses derived from the Prospective Investigation of the Vasculature in Uppsala Seniors (PIVUS) study also demonstrated a positive relationship between FGF23 and total body atherosclerosis in a sample of 70-year-old patients." (PMID 22590632, 2012). "To investigate whether serum FGF23, α-klotho levels and FGF23/α-klotho ratio were associated with T2DM combined with atherosclerosis, we fitted ordered regression models and logistic regression models to assess the associations of the factors with atherosclerosis in patients with T2DM." (PMID 38622690, 2024). "Whether or not a direct causality exists between elevated FGF23 levels and subclinical atherosclerosis is a subject of some debate." (PMID 35629299, 2022).
atherosclerosis (continued). "The possible explanations could be that FGF-23 might facilitate the progression of atherosclerosis through several methods including regulating oxidative stress and proliferation of vascular endothelial cells, as well as promoting the infiltration of macrophages." (PMID 36132198, 2022). "The presence of FGF23 and α-klotho in patients with T2DM combined with atherosclerosis has important implications for the early prevention of T2DM and related complications." (PMID 38622690, 2024). "Indeed, a prolonged hyperglycemic state activates oxidative stress pathways, subsequently causing vascular endothelial damage and ultimately leading to the formation of plaques, suggesting that the relationship between FGF23 or α-klotho and atherosclerosis may be partially driven by hyperglycemia." (PMID 38622690, 2024). "FGF23, HO1, PGF, and CD40L were related to cardiovascular damage, such as atherosclerosis and infarction." (PMID 38958674, 2024). "FGF23, α-klotho and their combination have certain predictive effects on T2DM and T2DM with atherosclerosis." (PMID 38622690, 2024). "The results suggested that the combination of FGF23 and α-klotho not only improved the prediction probability of T2DM, but also improved the diagnosis rate of T2DM combined with atherosclerosis." (PMID 38622690, 2024). "Fibroblast growth factor-23 (FGF23) and its co-receptor, Klotho, are thought to have a central role in atherosclerosis and CKD-MBD." (PMID 36769771, 2023). "High levels of FGF23 are positively correlated with increasing blood pressure and pulse pressure in CKD, this may be due to impairment of endothelial dependent vasorelaxation, High levels of FGF23 are associated with arterial stiffness, atherosclerosis and aortic valve calcifications in CKD." (PMID 34600515, 2021). "Additionally, studies have found that people with an eGFRcys/eGFRcr ratio <0.6 have higher levels of proteins related to atherosclerosis and cell proliferation, such as IL-6, CXCL10 and FGF23." (PMID 40235956, 2025). "Additionally, markers of neurodegeneration (τ protein and amyloid β-1-40), some vascular inflammation (FGF-23 and FGF-21), and atherosclerosis (LOX-1) demonstrated correlational relationships with MCP-1." (PMID 40904362, 2025). "When predicting T2DM combined with CIMT, the AUC of FGF23 was the highest (AUC: 0.6593), likewise, the combined group maintained the highest prediction probability (AUC: 0.6283) when we predicted T2DM combined with atherosclerosis." (PMID 38622690, 2024). "Fibroblast growth factor-23 (FGF-23) mediates vascular endothelial injury, inflammatory infiltration, and atherosclerosis, which could reflect major adverse cardiac and cerebrovascular event (MACCE) risk in several cardiovascular diseases." (PMID 36132198, 2022). "In conclusions, a first-degree FHD contributes to an increase in serum FGF23 levels, independent of the presence of subclinical atherosclerosis and cardiovascular factors." (PMID 27698482, 2016). "Although the role of FGF23 in the development of atherosclerosis is suggested, there has been no clinical evidence about FGF23 levels and carotid plaque stability." (PMID 26459301, 2015). "The hypothesis that early MBD, marked by increased plasma concentrations of FGF-23,would influence the atherosclerosis process in patients with primaryglomerulonephritis was not confirmed in our evaluation, which wascross-sectional." (PMID 36638246, 2024). "However, the impact of FGF-23 on the early stages of atherosclerosis in patients with gestational diabetes is not defined." (PMID 30462803, 2018). "Furthermore, both FGF23 and FGF23/α-klotho ratio were positively correlated with CIMT and atherosclerosis in T2DM patients, while α-klotho was inversely correlated with both CIMT and atherosclerosis, although the associations were not completely significant." (PMID 38622690, 2024). "Therefore, the role of FGF23 on atherosclerosis has not been reliably determined." (PMID 38732094, 2024).
atherosclerosis (continued). "Similarly, it is unknown if FGF23 might or might not promote changes on the VSMC phenotype, with loss of vascular function, atherosclerosis, or even arterial stiffness." (PMID 32188018, 2020). "The potential of mineral metabolic disturbances, including FGF23, α-klotho, PTH, phosphate, and vitamin D status, as non-traditional biomarkers of atherosclerosis is still under debate." (PMID 36221075, 2022). "However, we lacked the data of FGF23 and Vitamin D. Further studies are warranted to determine the role of CKD-MBD in the link between atherosclerosis and kidney stone formation." (PMID 32182704, 2020). "Indeed, the relationship, if any, of the main mineral metabolism factors (i.e., calcium, phosphate, 25-hydroxyvitamin D (vitamin D), FGF23, a-klotho, PTH) with subclinical atherosclerosis burden in T1D subjects, in the absence of kidney impairment has not been assessed yet." (PMID 36221075, 2022).
Obesity (67 papers, 2013 to 2025). Accumulation of substantial excess body fat. "Studies have demonstrated associations between FGF23, obesity, and kidney disease, with FGF23 positively correlated with total body fat percentage, visceral fat, and male-pattern adipose tissue while showing a negative correlation with lean body mass." (PMID 40416622, 2025). "Both FGF23 and ER stress have been implicated as contributing factors to conditions like overweight and obesity, which are often found in XLH." (PMID 39329699, 2024). "In the univariable analysis, age, obesity, dyslipidemia, and statin use were significantly associated with higher circulating FGF23 levels." (PMID 37627287, 2023). "By contrast, obesity and insulin resistance are associated with elevated FGF-23 plasma concentrations in adults." (PMID 36437429, 2023). "Authors found that higher FGF23 levels were associated with obesity, dyslipidemia (lower HDL cholesterol and apolipoprotein A1, higher triglyceride), and increased risk of presenting metabolic syndrome." (PMID 34208131, 2021). "Overall, they found evidence that the association between FGF23 and CV risk can be partially mediated by obesity and dyslipidemia, both well-established CVD risk factors." (PMID 34055103, 2021). "A previous study reported that FGF23 was associated with insulin resistance, obesity, hyperlipidemia, and visceral adiposity." (PMID 30228288, 2018). "Our findings suggest independent associations of FGF23 with insulin resistance, inflammation, and obesity, particularly among individuals with normal kidney function." (PMID 25811862, 2015). "We aimed to investigate whether HFD feeding and obesity is associated with gastric FGF23 production." (PMID 40483378, 2025). "Moreover, FGF23 has been associated with obesity, dyslipidemia, visceral adiposity, insulin resistance, and an increased risk of metabolic syndrome." (PMID 38791495, 2024). "Recently, altered plasma concentrations of FGF-23 were linked to insulin resistance and obesity." (PMID 36437429, 2023). "We want to underline that FGF23 is increased in subjects with obesity." (PMID 36221075, 2022). "FGF23 was associated with markers of obesity, MS, insulin levels, and HOMA-IR index." (PMID 34208131, 2021). "However, FGF23 has also been associated with obesity, dyslipidemia, visceral adiposity, IR markers, and an increased risk of metabolic syndrome both in childhood and in adult populations." (PMID 34208131, 2021). "The association of FGF-23 concentrations with obesity and insulin resistance is unclear, possibly because some studies reporting positive associations with BMI measured total FGF-23 (full-length and C-terminal fragments) instead of measuring intact FGF-23 as we have done." (PMID 31652917, 2019). "In fact, FGF23 has been shown to be associated with markers of insulin resistance, dyslipidemia and obesity, suggesting the FGF23 could be a cardiometabolic risk factor connecting obesity and higher cardiovascular complications." (PMID 28331532, 2017). "Obesity status-associated IR may induce high circulating intact (iFGF-23) and C-terminal FGF-23 (CtFGF-23), which is positively associated with PTH and negatively associated with vitamin D, resulting in low bone mass." (PMID 23983685, 2013). "We first explored the possible association of serum FGF-23 concentrations with obesity." (PMID 23555610, 2013). "Additionally, obesity is a risk factor for cancers in at least 13 sites in humans, and obesity has been associated with increased dietary phosphate and elevated serum levels of hormones that regulate Pi metabolism: fibroblast growth factor 23 (FGF23) and parathyroid hormone (PTH)." (PMID 38392693, 2024). "However, the strong effect of both urinary lactulose and fecal MPO on FGF21 and FGF23, adipokines associated with increased intestinal permeability in mice and obesity in humans, suggests a complex interrelationship between these risk factors in the early pathogenesis of MetS." (PMID 36096405, 2022).